EIF3B (eukaryotic translation initiation factor 3 subunit B)
Diseases named in the same sentence as EIF3B in open-access papers (continued):
Sharing a sentence is not in itself a finding about the gene and the disease.
tumor (continued). "Then, by constructing a xenograft model, it was confirmed that the inhibition of eIF3b could also inhibit tumour proliferation and metastasis in vivo." (PMID 31423012, 2019). "In this study, we uncovered its potential correlation with eIF3b in tumor as a CTA." (PMID 31481019, 2019). "In addition, in vivo, tumor xenograft assay was performed to verify that EIF3B made a difference in the proliferation ability." (PMID 27270324, 2016). "Moreover, the tumor volume in mice of the EIF3B knockdown group was significantly decreased." (PMID 35459206, 2022). "Also, the effects of EIF3B knockdown on the tumor growth of PC were determined in vivo." (PMID 33996561, 2021). "Furthermore, the tumor growth of PC was inhibited after the knockdown of EIF3B in vivo." (PMID 33996561, 2021). "Other elements of EIF3 complex as well as translational machinery such as EIF3B, EIF3C, EIF4A, EEF1A, and EEF2 were already revealed as components of tumor-associated exosomes, which implicates exosomal delivery of translational machinery including EIF3A can be involved in tumor propagation." (PMID 31363116, 2019). "To validate the in vivo roles of EIF3B and MAP2K2, we established subcutaneous xenograft tumor models in mice." (PMID 40691141, 2025). "Meanwhile, we conducted IHC staining experiments on tumor tissues (n = 123) and paired normal tissues (n = 41) of clinical LSCC patients to clarify the expression intensity of EIF3B." (PMID 40691141, 2025). "Collectively, these data establish a linear signaling axis where EIF3B enhances ERK/MAPK signaling via MAP2K2-mediated MEK activation, thereby driving tumor cell proliferation." (PMID 40691141, 2025). "To further clarify that EIF3b is downstream of PUS1 regulation, we knocked down EIF3b in DU145 and PC-3 cell lines and observed a significant decrease in the migration and invasion abilities of the tumor cells." (PMID 39247811, 2024). "Difference is found in the expression of EIF3A, EIF3B, EIF3D, EIF3F, EIF3H, EIF3J, and EIF3M in different tumor stages." (PMID 36051357, 2022). "In vitro and in vivo studies into the downregulation of EIF3B showed the inhibition cell proliferation and clonogenicity in SGC7901 and BGC823 cells lines, and knockdown of EIF3B notably abated the tumor volume and weight in an SGC7901 xenograft mouse model." (PMID 33066449, 2020). "In clinical features, tumor depth, lymph node metastasis and TNM stage were positively correlated with EIF3B expression, significantly (P < 0.05)." (PMID 27270324, 2016). "Notably, EIF3B’s prognostic value in LSCC surpasses that of conventional markers like EGFR, which shows moderate correlation with tumor size but lacks specificity for aggressive subtypes." (PMID 40691141, 2025). "Moreover, knockdown EIF3B and control AMC-HN-8 cells were injected subcutaneously into nude mice to analyze the effects on tumor formation." (PMID 40691141, 2025). "To investigate whether EIF3b serves as a substrate for TTC3-mediated ubiquitination degradation, we transiently transfected TTC3 into tumor cells and observed a significant decrease in endogenous EIF3b protein levels." (PMID 39247811, 2024). "The analysis shows that the mRNA expression of eIF3b was not related to the patient’s age or gender but was related to the stage and progression of the tumour." (PMID 31423012, 2019). "Except EIF3E and EIF3F found down-regulated and conferred tumor suppressive activity in cancers, majority of EIF3 members including EIF3A, EIF3B, EIF3C, EIF3D, EIF3H, EIF3I and EIF3M were up-regulated and played important roles in tumor progression of multiple cancer types." (PMID 29568350, 2018). "EIF3B is an important part of the EIF3 complex, involved in tumor formation." (PMID 22734884, 2012).
tumor (continued). "Besides, nine eIF3 subunits beyond eIF3D were found aberrantly expressed in LUAD tissues and in which the expression levels of five subunits (eIF3B, eIF3C, eIF3E, eIF3H, and eIF3J) increased in LUAD patients with high tumour stage, implicating their roles in the maintenance or progression of LUAD." (PMID 31885740, 2019). "The exact pathway for EIF3B to accelerate the malignant tumor progression has not been announced." (PMID 27270324, 2016).
cancer (26 papers, 2015 to 2025). A tumor composed of atypical neoplastic, often pleomorphic cells that invade other tissues. "eIF3b has been shown to be overexpressed in prostate and bladder cancers, and its overexpression is associated with cancer prognosis." (PMID 31423012, 2019). "And EIF3B was chosen for mutation analysis via the Cancer SEA online tool." (PMID 35040374, 2022). "This aligns with emerging evidence of EIF3B’s oncogenic roles in other cancers, where EIF3B overexpression correlates with metastasis and reduced survival." (PMID 40691141, 2025). "This contrasts with its classical role as a translation initiation factor but aligns with emerging evidence of EIF3B’s multifunctionality in cancer biology." (PMID 40691141, 2025). "Functionally, ablation of EIF3B potently inhibited cancer cell proliferation, colony formation, and migratory abilities." (PMID 40691141, 2025). "EIF3B is evidently overexpressed in various human cancers and acts as an oncogene to promote their invasion and metastasis." (PMID 35273605, 2022). "EIF3B is a member of the eukaryotic translation initiation factor 3 subunit B and is related to the transcription initiation of cancer-related genes." (PMID 33142921, 2020). "eIF3b is the main scaffolding subunit in the eIF3 complex and has been demonstrated to contribute to the development of several cancers." (PMID 31423012, 2019). "In oesophageal squamous cell carcinoma, eIF3b promoted cancer progression by activating the β-catenin signalling pathway." (PMID 31423012, 2019). "Upregulation of eIF3a, eIF3b, eIF3c, eIF3d, eIF3e, eIF3h, and eIF3i along with reduced levels of eIF3e and eIF3f has been observed in several cancers." (PMID 28083147, 2016). "Additionally, the migration ability of EIF3B down-regulated LSCC cells AMC-HN-8 and TU212 decreased sharply within 24 h after starvation treatment, underscoring the critical role of EIF3B in facilitating the aggressive behavior of these cancer cells." (PMID 40691141, 2025). "In addition, submap analyses supported that low EIF3B expression was correlated with partial response to anti-PD1 therapy, and correlation analyses showed that EIF3B expression was negatively correlated with the steps in the cancer immunity cycle." (PMID 35273605, 2022). "Elevated expression of EIF3B was observed in the HNSCC cancer samples." (PMID 35459206, 2022). "Therefore, we further analyzed the correlation between EIF3B expression and anti-cancer immunity cycle and found EIF3B expression was negatively correlated with all the steps in the cycle." (PMID 35273605, 2022). "EIF3B expression was elevated in the HNSCC cancer samples compared with the control normal samples." (PMID 35459206, 2022). "Moreover, the Tex261 family contains many members, among which Tex9 is believed to cooperate with eIF3b to promote proliferation and inhibit apoptosis of esophageal squamous cells and carcinoma occurrence by activating the AKT signaling pathway." (PMID 36408272, 2022). "Although the effects of EIF3B on other cancers have been analyzed, whether EIF3B played a role in human PC has not been explored yet." (PMID 33996561, 2021). "Moreover, eIF3b is abnormally expressed and plays an important role in the invasion and migration of cancer cells in osteosarcoma, oesophageal squamous cell carcinoma and renal cell carcinoma." (PMID 31423012, 2019). "These conflicts suggested that the effect of EIF3B expression on cell cycle might be specific to cancer type." (PMID 27270324, 2016). "Thus, the overexpression of eIF3a, eIF3b, or eIF3c subunits stimulates the expression of other eIF3 subunits that further supports the translational components necessary for faster cancer cell growth." (PMID 28083147, 2016). "Furthermore, EIF3B was demonstrated as a critical regulator of cell cycle in cancer progression." (PMID 37020555, 2023). "However, the functions of EIF3B in other types of human cancers such as PC were uncertain." (PMID 33996561, 2021).
cancer (continued). "EIF3B as a promising therapeutic target may have similar effects to EIF5A in cancer treatment." (PMID 33996561, 2021). "Based on the BRCA data from the TCGA database, we confirmed the higher expression of EIF3B compared in 112 pairs of BRCA tissues and matched non-cancer tissues, and the EIF3B expression level was significantly related to the pathologic stage." (PMID 35040374, 2022). "Among the RBPs identified, several were selected based on their detection intensity, relevance to extracellular vesicles, and reported connections to human cancer, including SRSF1, EIF3B, and TIA1." (PMID 32819370, 2020). "eIF3i expression is also significantly increased by ~5 fold in cancer compared with their matched normal tissues, consistent with the previous finding, Interestingly, the expression of both eIF3b and eIF3g did not change significantly between cancer and normal tissues." (PMID 39413959, 2024).
infection (8 papers, 2009 to 2025). The state of being infected such as from the introduction of a foreign agent such as serum, vaccine, antigenic substance or organism. "After the infection of lentivirus, the effects of EIF3B knockdown on cell apoptosis and cell cycle were further examined by flow cytometry." (PMID 33996561, 2021). "By this time after infection, a similar localization was found for other translation initiation or elongation factors such as eIF3b, eIF2α and eEF2." (PMID 19714237, 2009). "AGS cells were infected with Hp11637 and Hp26695 at a ratio of 100:1, and the qRT-PCR results show that both of the H. pylori strains upregulated the expression of eIF3b mRNA in AGS cells, especially 12 h after the infection." (PMID 31423012, 2019). "A murine norovirus (MNV) infection was reported to inhibit SG formation, but foci containing G3BP1 but not eIF3B were observed near the viral replication sites." (PMID 40548742, 2025). "Analysis of earlier time points at 2, 4, 6 or 8h post infection confirmed this with complete absence of G3BP1 and eIF3B positive SGs during MNV infection." (PMID 31905230, 2020).
neurodevelopmental disorder (2 papers, 2025). A behavioral and cognitive disorder with onset during the developmental period that involves impaired or aberrant development of intellectual, motor, or social functions. "Integrating the findings from our human cohort and zebrafish models, we propose that haploinsufficiency of either EIF3A or EIF3B causes an eIF3-related cardiovascular, craniofacial, and neurodevelopmental disorder." (PMID 41033306, 2025).
EIF3B also shares sentences with these, for which no sentence is quoted: head and neck cancer (2 papers); Acute hepatitis (1); age (1); autoimmune disease (1); brain tumor (1); cervical cancer (1); clear cell renal cell carcinoma (1); cleft palate (1); colon adenocarcinoma (1); developmental delay (1); endometrial cancer (1); Failure to thrive (1); Helicobacter pylori (1); invasive breast carcinoma (1); leukemia (1); leukodystrophies (1); liver diseases (1); nasopharyngeal carcinoma (1); renal carcinoma (1); testicular cancer (1); triple-negative breast carcinoma (1); Ulceration (1).